NR4A1 (nuclear receptor subfamily 4 group A member 1)
Diseases named in the same sentence as NR4A1 in open-access papers (continued):
Sharing a sentence is not in itself a finding about the gene and the disease.
viral infection (9 papers, 2014 to 2026). "Although contribution of NR4A1 in the innate immune response has been demonstrated, its role in host defense against viral infection remains to be investigated." (PMID 29053748, 2017). "This prompted us to evaluate whether treatment of IAV-infected mice with the NR4A1 agonist Csn-B may control viral infection and reduce excessive lung inflammation." (PMID 29053748, 2017). "Moreover, we also overexpressed NR4A1 in islets from wild-type mice by viral infection with Ad-NR4A1." (PMID 26157144, 2015). "Therefore, in light of the results obtained, we can postulate that treatment with Csn-B (and consequently activation of NR4A1) controls the spread of viral infection and also protects from morbidity and from excessive lung inflammation induced by IAV infection." (PMID 29053748, 2017). "Western blot analysis revealed a significant decrease of Nr4a1 level in the hippocampi of mice injected with AAV-si-Nr4a1 compared to those injected with AAV-vector, confirming successful viral infection." (PMID 40468463, 2025). "Since FOS, FOSB and NR4A1 gene expression was consistently lacking in epithelial transcriptional responses to SARS‐CoV‐2, we next investigated their contribution to viral infection by modulation of their activity, or modulation of related signalling pathways, using small molecules." (PMID 38623540, 2024).
Arthritis (8 papers, 2008 to 2026). Inflammation of a joint. "In a serum transfer-induced arthritis (STIA) model NR4A1-dependent Ly6C- monocytes contribute to reducing joint inflammation in arthritic mice through the mobilization of Treg cells." (PMID 35935773, 2022). "Nr4a2 and Nr4a3 expression is up-regulated only in synovial fluid neutrophils elicited by STIA arthritis, and Nr4a1 expression is up-regulated in STIA and to a lesser extent in TG neutrophils." (PMID 35935773, 2022). "Results from NR4A1-KO mice indicate that inflammatory Ly6Chigh monocytes contribute to a mouse model of arthritis; in NR4A wild-type mice, CsnB increases levels of CD4+, CD25+, and FOXP3+ Treg cells in the presence of Ly6Clow monocytes to inhibit progression of arthritis." (PMID 40871737, 2025).
cervical carcinoma (8 papers, 2014 to 2025). A carcinoma arising from either the exocervical squamous epithelium or the endocervical glandular epithelium. "Importantly, a recent study revealed that NR4A1 implicated in the anti-tumor effect to induce cell apoptosis in cervical cancer." (PMID 36566195, 2022). "Di(1H-indol-3-yl) (4-(trifluoromethyl)phenyl)methane (BI1071) binds to NR4A1 and induces the association between NR4A1 and Bcl-2, leading to NR4A1 translocation to mitochondria and apoptosis induction in mouse embryonic fibroblasts and human cervical carcinoma cell line HeLa." (PMID 40746844, 2025). "NR4A1 can also bind to Bcl-B and BFL-1, and NR4A1 interaction with Bcl-B or BFL-1 leads to apoptosis in the human cervical carcinoma cell line HeLa." (PMID 40746844, 2025). "In contrast, 9-cis-retinoic acid induces NR4A1/RXRα heterodimer formation and NR4A1 and RXRα translocation to mitochondria in human cervical carcinoma cell line HeLa." (PMID 40746844, 2025). "This is consistent with our results, and implies that NR4A1 acts as a tumor suppressor in modulating the malignant phenotype of cervical cancer cells." (PMID 36566195, 2022). "Our findings reveal that m6A regulates cervical cancer cellular progression through manipulating NR4A1 pathway." (PMID 36566195, 2022).
Hepatic steatosis (8 papers, 2013 to 2025). Steatosis is a term used to denote lipid accumulation within hepatocytes. "Abnormal liver expression of NR4A1 is implicated in fat metabolism, cholesterol metabolism, hepatic steatosis, and many other pathophysiological processes." (PMID 33328994, 2020). "The abnormal expression of NR4A1 in the liver is implicated in numerous pathophysiological processes, including fat metabolism, cholesterol metabolism, and hepatic steatosis." (PMID 30013988, 2018). "For example, NR4A1 protects against homocysteine-induced hepatic steatosis, drug-induced liver injury, ischemic reperfusion injury, hypoxia–reperfusion injury, TGFβ-induced fibrosis, and genetic-induced liver damage." (PMID 40871737, 2025). "In the liver, NR4A1 is involved in gluconeogenesis and increased blood glucose levels, and deletion of the receptor enhances hepatic steatosis and increases expression of lipogenic genes." (PMID 40871737, 2025). "Full-body NR4A1 knockout mice fed with a high-fat diet showed elevated liver triglycerides, cholesterol, and exacerbated hepatic steatosis." (PMID 33328994, 2020). "Hepatic steatosis and the expression of lipogenic genes increase significantly in NR4A1 null mice fed a high-fat diet." (PMID 30013988, 2018). "The published study supports this mechanistic insight, showing that PS-MPs activate NR4A1, a nuclear receptor that acts upstream of AMPK signalling, contributing to an energy metabolism imbalance and hepatic steatosis." (PMID 41142238, 2025).
multiple sclerosis (8 papers, 2015 to 2025). A progressive autoimmune disorder affecting the central nervous system resulting in demyelination. "Knockout of NR4A1 displays earlier onset and more severe clinical experimental autoimmune encephalomyelitis, which is related to multiple sclerosis." (PMID 40746844, 2025). "Thus NR4A1 is an endogenous inhibitor in this model of induced multiple sclerosis and this is due, in part, to repression of norepinephrine and Th expression; a more recent study showed similar functions for NR4A1 in CNS autoimmunity." (PMID 40871737, 2025). "Moreover, the loss of NR4A1 enhanced experimental autoimmune encephalomyelitis in mice compared to wild-type mice, and in mice expressing NR4A1, treatment with CsnB inhibited the course of this disease model for multiple sclerosis." (PMID 40871737, 2025). "NR4A1 expression in peripheral blood mononuclear cells was low during the preclinical stage of multiple sclerosis, and INF-γ and IL-17 production by proinflammatory Th1/Th17 cells in the central nervous system was decreased after NR4A1 agonist cytosporone B treatment." (PMID 41462398, 2025). "In addition, in multiple sclerosis patients, 1,25(OH)D could activate repressed apoptosis via NR4A1 expression, potentially leading to better disease control by destroying autoreactive cells." (PMID 40823027, 2025).
osteoarthritis (8 papers, 2016 to 2025). A noninflammatory degenerative joint disease occurring chiefly in older persons, characterized by degeneration of the articular cartilage, hypertrophy of bone at the margins and changes in the synovial membrane. "Inflammation associated with osteoarthritis in humans was accompanied by increased expression of NR4A1 and overexpression of several MMPs, COX-2, and iNOS." (PMID 40871737, 2025). "In the present study, we demonstrated that NR4A1 was a key checkpoint for inflammatory response and the failure of its negative regulatory ability existed in advanced osteoarthritis." (PMID 32258036, 2020). "In the present study, we demonstrated the NR4A1 as a key negative regulator for controlling NF-κB pathway in chondrocytes and osteoarthritis." (PMID 32258036, 2020). "Reactivation of NR4A1 by its specific agonist Cytosporone B can rebalance chondrocyte inflammatory response in vitro and ameliorate osteoarthritis in vivo." (PMID 32258036, 2020). "In the present study, our data revealed that the expression of NR4A1 was also elevated in osteoarthritis cartilage tissue through the activation of NF-κB signal pathway." (PMID 32258036, 2020). "In the present study, we observed that NR4A1 was phosphorylated in osteoarthritis tissue or through in vitro inflammatory stimulation, which was significantly blocked by p38, ERK and JNK inhibitors." (PMID 32258036, 2020). "Our study partially explained the mechanism of chronic chondrocyte inflammation in osteoarthritis and demonstrated NR4A1 as a potential therapeutic target for OA treatment." (PMID 32258036, 2020). "Furthermore, NR4A1 inhibits inflammation and matrix metalloproteinases' expression in chondrocytes and attenuates osteoarthritis." (PMID 40746844, 2025). "The reactivation of NR4A1 by its agonist cytosporone B could prevent chondrocyte inflammation and ameliorate osteoarthritis in vitro and in vivo." (PMID 32258036, 2020). "In the present study, we found that the NR4A1 expression was elevated in human osteoarthritis cartilage and in vitro OA model, which could be blocked by NF-κB signal inhibitor JSH23." (PMID 32258036, 2020). "Thus, NR4A1 was relatively inactivated in osteoarthritis and thereby the NF-κB signal got out of the physiological negative regulation by NR4A1." (PMID 32258036, 2020). "The orphan nuclear receptor 4A1 (NR4A1) is a key negative regulator of inflammatory responses but its role in osteoarthritis remains unclear." (PMID 32258036, 2020). "The phosphorylation of NR4A1 was increased in human osteoarthritis cartilage, and p38 inhibitor SB203580, JNK inhibitor SP600125 and ERK inhibitor FR180204 could significantly inhibited IL-1β induced NR4A1 phosphorylation." (PMID 32258036, 2020). "In vitro overexpression and knockdown experiments demonstrated that NR4A1 could inhibit the p65 transcriptional ability and prevent the IL-1β induced MMPs expression in chondrocytes, thus indicating a protective role of NR4A1 in osteoarthritis." (PMID 32258036, 2020). "NR4A1 agonist cytosporone B could reactivate and restore the inhibitory regulatory ability of NR4A1, prevent excessive inflammation, and ameliorates osteoarthritis." (PMID 32258036, 2020). "For instance, NR4A1 reactivation by its agonist cytosporone B could inhibit IL-1β induced chondrocyte inflammation, and injection of cytosporone B protected cartilage damage and alleviated osteoarthritis in rat osteoarthritis model." (PMID 34924813, 2021). "Thus inflammation could phosphorylate and inactivate NR4A1 in osteoarthritis through the activation of MAPK pathway." (PMID 32258036, 2020). "Further, if the existence of cluster O3 is due to the osteoarthritis, specific markers NR4A1 and NR4A2, would have important roles in osteoarthritis pathogenesis." (PMID 34428745, 2021). "To investigate the function and mechanism of NR4A1 in osteoarthritis, we firstly detected the expression of NR4A1 and p65 in normal and OA cartilage by western blot and RT-PCR." (PMID 32258036, 2020).
osteoarthritis (continued). "In conclusion, we demonstrated that the NR4A1 is a key endogenous inhibitor of chondrocyte inflammation, which was relatively inactivated under chronic inflammatory stimulation through HDACs mediated transcriptional suppression and MAKP dependent phosphorylation in osteoarthritis." (PMID 32258036, 2020). "Thus, our study demonstrated that the NR4A1 is a key endogenous inhibitor of chondrocyte inflammation, which was relatively inactivated under chronic inflammatory stimulation through HDACs mediated transcriptional suppression and MAKP dependent phosphorylation in osteoarthritis." (PMID 32258036, 2020). "While previous studies have reported NR4A1 and NR4A2 to be regulators of inflammatory responses in chondrocytes, no study has proposed the relationship between osteoarthritis and NR4A1 produced by osteoblasts." (PMID 34428745, 2021).
rheumatoid arthritis (8 papers, 2016 to 2025). A chronic, systemic autoimmune disorder characterized by inflammation in the synovial membranes and articular surfaces. "Furthermore, NR4A1 expression is associated with attenuated inflammatory cell infiltration and synovial hypertrophy in collagen-induced arthritis rats, suggesting a protective role for NR4A1 in the progression of rheumatoid arthritis." (PMID 40746844, 2025). "NR4A1 is involved in regulating extracellular matrix, tolerance, and inhibition of phagocytosis in bone marrow-derived macrophages, indicating the protective effect of NR4A1 against multiple chronic inflammatory joint diseases such as rheumatoid arthritis, which are affected by macrophages." (PMID 40746844, 2025). "The KEGG analysis showed that the downregulated genes at day 3 Cracr2b, Nr4a1, Fos, Jun, Vegfa were involved in the MAPK signalling pathway, Nr4a1, Fos, Jun were involved in the relaxin signalling pathway, chemical carcinogenesis-receptor activation, and rheumatoid arthritis." (PMID 36445632, 2023).
Stroke (8 papers, 2012 to 2025). Sudden impairment of blood flow to a part of the brain due to occlusion or rupture of an artery to the brain. "In this respect the young rats had more genes encoding neuroprotective factors (Fgf9, Nr4a1, Tpm3) that had recovered by day14 post-stroke suggesting a better control of adult brain plasticity in young animals." (PMID 23251410, 2012). "NR4A1 is also involved in post-stroke recovery, and deletion of NR4A1 in microglia results in increased expression of TNF and this results in increased brain injury." (PMID 40871737, 2025). "High-salt treatment impaired the resolution of the intracranial hematoma. and polarized macrophages to a less reparative phenotype.Downregulation of NR4a1 in macrophages mediates the HS effects on stroke recovery." (PMID 38396989, 2024). "Collectively, these results indicate that microglial NR4A1 suppresses Tnf expression and alleviates microglia-potentiated neuronal damage after stroke." (PMID 37486903, 2023). "Global and conditional microglial knockout of Nr4a1 up-regulated Tnf expression and worsened stroke outcomes." (PMID 37486903, 2023). "Specifically, we identified the orphan nuclear receptor 4A1 (NR4a1/Nur77) as a potential therapeutic target for alleviation of HSD‐induced adverse effects on stroke recovery." (PMID 37965920, 2023). "Nevertheless, our studies indicated that Tnf was significantly affected by NR4A1-deletion in rodent stroke model, while NR4A1 regulates multiple proinflammatory cytokines in in vitro-activated microglia." (PMID 37486903, 2023). "Furthermore, NR4A1 is significantly induced in the cytoplasm of microglia after ischemia and contributes to the suppression of post-stroke Tnf up-regulation, leading to improved outcomes." (PMID 37486903, 2023). "To assess whether this expression pattern can also be observed in stroke patients, we analyzed NR4A1 expression in postmortem brain sections obtained from patients after ischemic stroke by immunofluorescence staining." (PMID 37486903, 2023). "Thus, our study illustrates a novel mechanism that NR4A1 posttranscriptionally regulates Tnf expression in microglia and determines stroke outcomes." (PMID 37486903, 2023). "The work by Liu and colleagues is novel and intriguing as it identifies a previously unidentified role of NR4A1 as an RNA-binding protein, highlights a new regulatory mechanism of TNF expression in microglia, and underscores a key function of NR4A1 in microglial polarization and stroke outcomes." (PMID 37490433, 2023). "In addition, several behavioral tests were conducted to explore the effects of NR4A1 on neurological deficits after stroke." (PMID 37486903, 2023). "Although this study confirmed up-regulation of NR4A1 in microglia after stroke in postmortem human brains, it is unclear whether NR4A1 modulates TNF expression via the same posttranscriptional mechanism in human microglia." (PMID 37490433, 2023). "Notably, Nr4a1-/- mice had more severe neurological deficits than WT controls, as assessed by the modified neurological severity score (mNSS) test, the rotarod test, total distance traveled, and mean velocity 1, 3, and 7 days after stroke." (PMID 37486903, 2023). "Thus, compounds with the ability to induce NR4A1 expression may improve stroke progression and be potential candidates for stroke therapy." (PMID 37486903, 2023). "Similar to in vitro findings, the expression of NR4A1 was remarkably induced, mainly in the cytoplasm of microglia, in a middle cerebral artery occlusion (MCAO) mouse model and stroke patients." (PMID 37486903, 2023). "This study identified a key role of microglial NR4A1 as an RBP that posttranscriptionally regulates Tnf expression, providing a promising target for stroke treatment." (PMID 37486903, 2023). "Accordingly, our study identified microglial NR4A1 functions as an RBP to destabilize Tnf mRNA in an m6A-dependent manner and alleviates post-stroke neuroinflammation, highlighting the role of m6A in ischemic stroke." (PMID 37486903, 2023).
Stroke (continued). "Loss of NR4a1 in macrophages recapitulates HSD‐induced negative impacts on stroke outcomes while gain of NR4a1 enables stroke recovery in HSD animals." (PMID 37965920, 2023). "To characterize the expression pattern of NR4A1 in ischemic stroke, we used MCAO as a mouse model to mimic ischemic stroke in human and found that NR4A1 expression was significantly elevated in the penumbra at day 1 and day 3 post-stroke." (PMID 37486903, 2023). "Our data showed that in the peri-infarct tissue, more NR4A1 was localized in microglia in stroke patients than in non-stroke controls." (PMID 37486903, 2023). "Furthermore, in chimeric mice lacking the transcription factor NR4A1 in BM-derived cells, Ly6Clo monocytes were drastically reduced in the circulation, but Ly6Clo Mo/MΦ were still observed in the brain 14 days after stroke." (PMID 27814740, 2016).
asthma (7 papers, 2017 to 2025). "The major cellular contributors of multiple asthma-associated inflammatory mediators, such as Il33, Hmgb1, Retnla, and Ager were identified, and a cluster of novel allergy-associated molecules, such as Chia1, Nnat, and Nr4a1 were found in different lung epithelial cells." (PMID 35627266, 2022). "For instance, Belgapten inhibited AHR and inflammation in asthma models by targeting NR4A1 to suppress airway inflammation and mast cell activation." (PMID 40811488, 2025). "Nur77, also known as NR4A1, is reportedly involved in asthma and acute lung injury through the activation of inflammatory response via regulation of NF-κB signaling." (PMID 37405051, 2023).